TCF7L2 (transcription factor 7 like 2)
Diseases named in the same sentence as TCF7L2 in open-access papers (continued):
Sharing a sentence is not in itself a finding about the gene and the disease.
metastatic disease (3 papers, 2011 to 2024). "The expression patterns of MIR100HG, hnRNPA2B1 and TCF7L2 in CRC specimens from patients who progressed on cetuximab and patients with metastatic disease were analyzed by RNAscope and immunohistochemical staining." (PMID 35279145, 2022).
neuroblastoma (3 papers, 2016 to 2023). Neuroblastoma (NB) is the most common solid, extracranial childhood tumor. "TCF7L2 and LEF1 are likely involved in the genesis of neuroblastoma, similar to TCF7L2 driving c-MYC-dependent intestinal tumorigenesis, but subsequently were sharply downregulated in MNA tumours and cell lines from metastatic neuroblastomas." (PMID 27531891, 2016). "Treatment of N2A cells with BMP4, a component of the Bmp pathway that is known to cross-talk with Wnt signalling in neuroblastoma, led to a 2.3-fold increase in Tcf7l2 and a subsequent 2.1- and 1.9-fold up-regulation in Paupar and Pax6 expression 72 hours later." (PMID 35709096, 2022). "The negative correlation between MYCN expression and LEF1 and TCF7L2 expression seen in the cell lines was also observed in the neuroblastoma tumours, confirming the functional MYCN-Wnt interactions revealed in the cell line data." (PMID 27531891, 2016). "Finally, treatment of N2A cells with RSPO2, a leucine rich repeat-containing G-protein coupled receptor (LGR) ligand that has been shown to amplify Wnt signal in a subset of neuroblastoma cells, did not induce significant changes in either Tcf7L2, Paupar or Pax6." (PMID 35709096, 2022).
osteoporosis (3 papers, 2013 to 2023). A condition of reduced bone mass, with decreased cortical thickness and a decrease in the number and size of the trabeculae of cancellous bone (but normal chemical composition), resulting in increased fracture incidence. "Importantly, BMSCs isolated from patients with osteoporosis showed a decrease in histone H3K18la lactylation and the expression of the target genes COL1A2, COMP, ENPP1, and TCF7L2." (PMID 37752768, 2023). "qPCR analysis of the target genes of H3K18la lactylation indicated that the expression of the osteogenic genes COL1A2, COMP, ENPP1, and TCF7L2 was decreased in BMSCs isolated from patients with osteoporosis compared with that in BMSCs from patients without osteoporosis." (PMID 37752768, 2023).
osteosarcoma (3 papers, 2022 to 2024). A usually aggressive malignant bone-forming mesenchymal neoplasm, predominantly affecting adolescents and young adults. "TCF7L2 (transcription factor 7 like 2) is a key factor in the Wnt signaling pathway, one of the 3 main cancer stem cell (CSC) pathways, and functions as an oncogene in osteosarcoma." (PMID 38254188, 2024).
autism spectrum disorder (2 papers, 2020 to 2023). A spectrum of developmental disorders that includes autism, and Asperger syndrome. "Specific TCF7L2 mutations have been associated with development disorders (DD) and autism spectrum disorder (ASD)." (PMID 36782064, 2023). "Patient mutations associated with developmental disorders, including autism spectrum disorders, disrupt the transcriptional repression effect of TCF7L2, while mice carrying those mutations display severe USV impairments." (PMID 36782064, 2023).
basal cell carcinoma (2 papers, 2019 to 2022). A carcinoma involving the basal cells. "At 36 dpi, 19 potential target mRNAs (e.g., tcf7l2, hpas, and map2k2) of six DEmiRNAs were associated with five enriched KEGG pathways (e.g., basal cell carcinoma, melanogenesis, and microRNAs in cancer)." (PMID 36230377, 2022). "For example, TCF7L2 (also known as TCF-4) from the basal cell carcinoma pathway plays a role in HIV latency maintenance and was up-regulated in the bystander model in our study." (PMID 31710657, 2019).
bowel cancer (2 papers, 2020 to 2021). "In human intestinal cancer cell lines Caco-2/TC7 and SW480 and normal crypt-like HIEC-6 cells, PrPc interacts with the canonical Wnt pathway effectors β-catenin and transcription factor 7-like 2 (TCF7L2) in the cytoplasm and nucleus to upregulate their transcriptional activities." (PMID 32992764, 2020).
cardiac hypertrophy (2 papers, 2021 to 2024). "In summary, it was inferred that EMPA treatment attenuates the TAC-induced cardiac hypertrophy by reducing the β-catening/TCF7L2 pathway." (PMID 39664517, 2024). "This research demonstrated that EMPA attenuates the progressive TAC-induced cardiac hypertrophy by directly binding to FZD to inhibit the Wnt/β-catenin/TCF7L2 signaling in cardiomyocytes, thereby protecting the heart from progressive HF." (PMID 39664517, 2024). "This study revealed that EMPA treatment can alleviate TAC-induced cardiac hypertrophy by directly inhibiting the FZD4/Wnt/β-catenin/TCF7L2 pathway in cardiomyocytes." (PMID 39664517, 2024). "Wnt/β-catenin/TCF7L2 pathway plays an important role in TAC-induced cardiac hypertrophy." (PMID 39664517, 2024). "Therefore, this study suggests that the Wnt/β-catenin/TCF7L2 signaling plays a critical role in EMPA-induced attenuation of TAC-induced cardiac hypertrophy." (PMID 39664517, 2024). "In the case of TCF7L2, it is found to be involved in cardiac hypertrophy through the Wnt/β-catenin signaling pathway, where it modulates the chromatin environment and regulates the expression of the slow Myh7 (MyHC-1) and the Wnt/β-catenin target, the Myc gene." (PMID 34752468, 2021). "Consistently, here, it was observed that EMPA treatment corrected the cardiac activation of the Wnt/β-catenin/TCF7L2 pathway, reversing the TAC-induced cardiac hypertrophy." (PMID 39664517, 2024). "In summary, EMPA treatment protects the heart from non-diabetic cardiac hypertrophy and HF by reducing the Wnt/β-catenin/TCF7L2 pathway." (PMID 39664517, 2024). "Therefore, EMPA may attenuate TAC-induced cardiac hypertrophy by binding FZD membrane protein, thereby inhibiting the Wnt/β-catenin/TCF7L2 signaling." (PMID 39664517, 2024).
cerebrovascular disease (2 papers, 2022 to 2024). "The genes related to cardiovascular and cerebrovascular disease annotated by the Hippo signaling pathway were Bmp4, Tcf7l2, and Wnt16." (PMID 38195688, 2024).
colon adenocarcinoma (2 papers, 2020 to 2025). "Furthermore, survival analyses based on gene expression (TCGA & GTEx profile) and mutational status (TCGA COAD & Pan‐cancer datasets) for colon adenocarcinoma identified CDKN2A, INHBA increased expression, and CDKN2A and TCF7L2 mutations as predictors of bad prognosis in metastatic patients." (PMID 40658092, 2025).
colorectal adenoma (2 papers, 2020 to 2025). An adenoma that arises from the colon or rectum. "Thus, the results obtained with the inactivation of Tcf7l2 in the small intestine could also be observed to a certain extent in colorectal adenomas." (PMID 40221753, 2025).
coronary atherosclerosis (2 papers, 2011 to 2021). Atherosclerosis of the coronary vasculature. "Previous studies have reported a statistically significant association between TCF7L2 gene polymorphism and DN and coronary atherosclerosis." (PMID 34193317, 2021). "In the present work, we report a positive association of the TCF7L2 variants rs7903146, rs12255372, and rs11196205 with coronary atherosclerosis, particularly in patients with T2DM." (PMID 21423583, 2011). "Potential links between genetic variants of the TCF7L2 locus and coronary atherosclerosis are uncertain." (PMID 21423583, 2011). "We therefore aimed at investigating the association of the TCF7L2 SNPs rs7903146, rs12255372, and rs11196205 with coronary atherosclerosis in a large cohort of well characterized consecutive patients undergoing coronary angiography." (PMID 21423583, 2011).
cystic fibrosis-related diabetes (2 papers, 2014 to 2025). Cystic fibrosis-related diabetes is a form of diabetes that occurs frequently in individuals with cystic fibrosis. "Several studies have also demonstrated that the genetic variants of TCF7L2 that drive T2D risk also increase susceptibility to cystic fibrosis-related diabetes (CFRD)." (PMID 24719615, 2014).
diabetic neuropathy (2 papers, 2025). A chronic, pathological complication associated with diabetes mellitus, where nerve damages are incurred due to diabetic microvascular injury involving small blood vessels that supply these nerves, resulting in peripheral and/or autonomic nerve dysfunction. "We also saw a signal at gene level with LHX8 and TCF7L2 and neuropathic pain in diabetic neuropathy." (PMID 39471050, 2025). "In addition, further research is needed to explore the roles of specific biomolecules implicated in diabetic neuropathy development, such as SLC30A1, TRBJ2‐7, OLFM1, TCF7L2, MCF2L, CEP295NL, CEACAM22P, TSHZ2, and PDZD4." (PMID 40692573, 2025).
endometriosis (2 papers, 2016 to 2025). The growth of functional endometrial tissue in anatomic sites outside the uterine body. "Although we initially focused on binding of TCF7L2 according to consistent results between the motif search and the ENCODE ChIP-seq analyses, SOX family members can be a good candidate for a regulator of the enhancer ability at the 9p21 endometriosis risk locus." (PMID 27055116, 2016). "Moreover, a significant downregulation of several potential targets, including CDK6, BCCIP, PTEN, TCF7L1, TCF7L2, ROBO1, COL4A2, E‐Cadherin, and N‐Cadherin, was observed in the transfected cells and endometriosis patients." (PMID 40135061, 2025).
gout (2 papers, 2017 to 2019). A condition characterized by painful swelling of the joints, which is caused by deposition of urate crystals. "Interestingly, three genes (PDZK1, GCKR and HNF4G) associated with urate influenced the risk of gout, but the other five genes (TCF7L2, LRRC16A, ESR1, NRXN2 and ALPK1) did not, suggesting that elevated serum urate concentration is necessary but not sufficient for the pathogenesis of gout." (PMID 28252667, 2017).
Infertility (2 papers, 2010 to 2024). "We speculate that perturbed Tcf7l2-dependent Wnt signaling might contribute to late-onset infertility in the absence of Sox9 in Sertoli cells." (PMID 21182756, 2010).
inflammatory bowel disease (2 papers, 2021 to 2025). A spectrum of small and large bowel inflammatory diseases of unknown etiology. "In contrast, the Tcf7l2 cKO mice harbored a substantial concentration of bacterial strains, including Enterococcus and Escherichia-Shigella, which are commonly found in patients with inflammatory bowel disease (IBD)." (PMID 40221753, 2025).
insomnia (2 papers, 2024). A sleep disorder characterized by difficulty in falling asleep and/or remaining asleep. "Of these genes, TRIM39, LINC02595, DKACD, and TCF7L2 were previously associated with OSA or insomnia in genome-wide association studies (GWAS)." (PMID 39457448, 2024).
insulinoma (2 papers, 2015 to 2016). "Nonetheless, the present results are consistent with very recent findings showing decreased expression of the voltage-gated calcium channel subunits including Cacna1d in rat insulinoma-derived INS1 β cells silenced for Tcf7l2." (PMID 25355422, 2015).
lung adenocarcinoma (2 papers, 2015 to 2026). A carcinoma that arises from the lung and is characterized by the presence of malignant glandular epithelial cells. "Consistent with its role as a Wnt/β-catenin effector, TCF7L2 displayed significant effect on lung adenocarcinoma cell growth." (PMID 41929079, 2026).
lymph node metastasis (2 papers, 2016 to 2019). "In addition, we found that rs290481 SNP in TCF7L2 gene increased the risk of lymph node metastasis in drinking patients with AEG." (PMID 31211453, 2019). "In addition, TCF7L2 rs290481 and INSR rs1799817 SNPs may influence the lymph node metastasis in AEG patients." (PMID 31211453, 2019). "In addition, TCF7L2 rs290481 and INSR rs1799817 SNPs may influence the lymph node metastasis in patients with AEG." (PMID 31211453, 2019).
myeloid leukaemia (2 papers, 2017 to 2018). "Notably, TCF7L2 plays a crucial role in maintaining the proliferation and viability of myeloid leukaemia cells, and overexpression of TCF7L2 is associated with poor clinical outcome." (PMID 29385209, 2018). "TCF7L2 maybe a valid target in myelogenous leukemia therapy." (PMID 29385209, 2018). "Many of those genes inhibited by SID peptide treatment (CD44, TGFβR2, LEF1, TCF7L2, FGF2, FGF5, ID2, PIK3R3) are known as direct TGIF1 targets in myeloid leukemia or embryonic stem cells." (PMID 29179446, 2017).
neuropathy (2 papers, 2023 to 2024). A disorder affecting the nervous system that manifests with pain, tingling, numbness, and/or muscle weakness. "TCF7L2 risk variants have also been reported to be associated with all diabetic microvascular complications, including retinopathy, nephropathy and neuropathy." (PMID 37452207, 2023).
osteoarthritis (2 papers, 2019 to 2023). A noninflammatory degenerative joint disease occurring chiefly in older persons, characterized by degeneration of the articular cartilage, hypertrophy of bone at the margins and changes in the synovial membrane. "Genetic variants associated with TCF7L2 expression in pancreatic islets and in osteoarthritis cartilage colocalize with this association signal." (PMID 37433298, 2023). "Variants in TCF7L2 have not been associated with osteoarthritis at genome-wide significance levels in the recent osteoarthritis GWAS (all variants in the credible set of the colocalization analysis achieve nominal significance in the recent knee osteoarthritis GWAS15)." (PMID 37433298, 2023).
psoriasis (2 papers, 2019 to 2021). An autoimmune condition characterized by red, well-delineated plaques with silvery scales that are usually on the extensor surfaces and scalp. "Associations between single nucleotide polymorphisms for WNT7B, WNT10B, WNT16 and TCF7L2 genes and psoriasis were tested." (PMID 31089877, 2019). "Previous studies have suggested that the TCF7L2 gene variant is associated with psoriasis." (PMID 35664972, 2021). "This study shows for the first time significant UVB induced upregulation of WNT7B, WNT10B and TCF7L2 in patients with psoriasis and suggests a potential role of these genes in psoriasis pathogenesis." (PMID 31089877, 2019). "Treatment with nbUVB induced a significant increase of WNT7B (p < 0.01), WNT10B (p < 0.001) and TCF7L2 (p < 0.01) gene expression in lesional skin of patients with psoriasis." (PMID 31089877, 2019). "Expression of TCF7L2 appeared to be similar in skin from healthy control subjects compared to non-lesional and lesional skin from patients with psoriasis." (PMID 31089877, 2019). "Gene expression analysis revealed significantly decreased WNT7B, WNT10B and TCF7L2 expression levels in lesional skin compared to non-lesional skin of patients with psoriasis (p < 0.001)." (PMID 31089877, 2019). "The functional contribution of WNT signaling to the pathophysiology of psoriasis needs to be studied further, but it can be speculated that WNT7B, WNT10B, TCF7L2 and WNT16 contribute to the pathogenesis of psoriasis." (PMID 31089877, 2019). "Levels of WNT7B, WNT10B, WNT16 and TCF7L2 gene expression in peripheral blood samples of patients with psoriasis were not significantly different compared to healthy individuals." (PMID 31089877, 2019). "The aim of this study was to describe the expression of WNT7B, WNT10B, WNT16 and TCF7L2 in lesional and non-lesional skin and in whole blood of patients with psoriasis compared to healthy individuals and to investigate if SNPs in these genes can be correlated to psoriasis." (PMID 31089877, 2019).
steatosis (2 papers, 2022 to 2025). Increased lipid within the cytoplasm of cells. "Transcription factor 7-like 2 (TCF7L2) suppresses CHREBP O-GlcNAcylation and liver-specific Tcf7l2 knockout mice exhibit exacerbated steatosis on high-carbohydrate diets due to unrestrained DNL." (PMID 40564141, 2025).
abdominal aortic aneurysm (1 paper, 2026). Enlargement and ballooning of the vessel that supplies arterial blood to the abdomen, pelvis and legs. "Here, we investigate transcription factor 7-like 2 (TCF7L2), a genetic locus associated with both thoracic and abdominal aortic aneurysms, to elucidate its role in AAA pathogenesis." (PMID 42060473, 2026).
acute coronary syndrome (1 paper, 2025). Signs and symptoms related to acute ischemia of the myocardium secondary to coronary artery disease. "We designed this study to explore whether the TCF7L2 gene variant rs77961654 A/C affects susceptibility to stable angina and acute coronary syndrome (ACS), and also the associations with clinical and biochemical characteristics in Chinese patients residing in Taiwan." (PMID 40303486, 2025).
B-cell lymphomas (1 paper, 2021). "In this study, we identified novel TCF7L2_WT1 gene fusion as one of the most frequently detected genomic aberrations in B-cell lymphomas." (PMID 34926267, 2021).
carbohydrate metabolism disorders (1 paper, 2022). "The aim of the present study was to explore the association of polymorphisms within MC4R, PPARG, and TCF7L2 with the risk of different carbohydrate metabolism disorders and changes in the body composition in overweight or obese patients with early carbohydrate metabolism disorders." (PMID 35292917, 2022).
Charcot arthropathy (1 paper, 2022). "TCF7L2 gene expression showed a significant reduction by 63% (p < 0.0001) and 18% (p = 0.0136) in diabetic Charcot arthropathy." (PMID 35436882, 2022). "In contrast the analyzed effector of Wnt signaling pathway TCF7L2 and osteocalcin acting downstream showed noticeable similarities between the T2DM and the Charcot arthropathy group." (PMID 35436882, 2022). "In this study, we could show a statistically significant decrease of the transcription of the TCF7L2 gene in the T2DM and also in thoseT2DM patients who suffered from Charcot arthropathy." (PMID 35436882, 2022). "For the first time significant changes in gene expression of the Wnt signaling pathway – namely WNT3A, WNT5A, TCF7L2 and osteocalcin- in the bone of patients suffering from T2DM and following Charcot arthropathy could be shown." (PMID 35436882, 2022).
ciliopathy (1 paper, 2022). A genetic disorder of the cellular cilia or the cilia anchoring structures, the basal bodies, or of ciliary function. "The targets of CREBP1 found from among the genes shared between the HLHS and ciliopathy interactomes were EP300, PRNP, SMAD3, SUMO1 and TBX6, while the targets of ALX4 were JUN and TCF7L2." (PMID 35456433, 2022).
cognitive deficits (1 paper, 2026). "At the molecular level, MASLD altered the expression of key hippocampal genes-including TCF7L2, LCN2, and AQP1-impacting immune response, lipid metabolism, and apoptotic pathways, which collectively contributed to cognitive deficits." (PMID 41674921, 2026).
colon adenoma (1 paper, 2017). An adenoma that arises from the colon.
Crohn ileitis (1 paper, 2013). A Crohn disease involving a pathogenic inflammatory response in the ileum. "Interestingly, reduction in TCF7L2 expression has also been reported in other intestinal disorders, particularly, ileal crohn’s disease (CD) or crohn's ileitis but not in colonic CD or ulcerative colitis." (PMID 23593167, 2013).